CAPZA1 (capping actin protein of muscle Z-line subunit alpha 1)
Description:
F-actin-capping proteins bind in a Ca(2+)-independent manner to the fast growing ends of actin filaments (barbed end) thereby blocking the exchange of subunits at these ends. Unlike other capping proteins (such as gelsolin and severin), these proteins do not sever actin filaments. May play a role in the formation of epithelial cell junctions. Forms, with CAPZB, the barbed end of the fast growing ends of actin filaments in the dynactin complex and stabilizes dynactin structure. The dynactin multiprotein complex activates the molecular motor dynein for ultra-processive transport along microtubules (By similarity).
Synonyms: CAPPA1; CAPZ; CAZ1
Tractability: Small molecule: a structure with a bound ligand is known. Antibody: its Gene Ontology location is reachable by antibodies, with high confidence. PROTAC: ubiquitination databases record sites on it; its protein half-life has been measured.
Gene: Protein-coding gene on chromosome 1 (112,619,173 to 112,671,616, forward strand). Ensembl gene ENSG00000116489.
Subcellular location: Cytoplasm, cytoskeleton
Pathways (Reactome):
Immune System: Advanced glycosylation endproduct receptor signaling; Gene and protein expression by JAK-STAT signaling after Interleukin-12 stimulation; MHC class II antigen presentation
Vesicle-mediated transport: COPI-independent Golgi-to-ER retrograde traffic; COPI-mediated anterograde transport
Cellular responses to stimuli: HSP90 chaperone cycle for steroid hormone receptors (SHR) in the presence of ligand
Hemostasis: Factors involved in megakaryocyte development and platelet production
Sensory Perception: Sensory processing of sound by inner hair cells of the cochlea
Gene Ontology:
Molecular function: cadherin binding; protein binding; actin binding; actin filament binding
Biological process: cell junction assembly; barbed-end actin filament capping; protein-containing complex assembly
Cellular component: extracellular exosome; F-actin capping protein complex; WASH complex; actin cytoskeleton; cortical cytoskeleton; cytoskeleton; cytosol; extracellular region
Genetic constraint (gnomAD): Loss-of-function variants: 1 observed, 14.42 expected, observed/expected ratio (o/e) 0.0694, 90% interval 0.024 to 0.33. The upper end of that interval is the gene's LOEUF score, 0.33, which puts it in group 1 of 6, group 1 being the genes least tolerant of losing a copy. Missense variants: 137 observed, 184.98 expected, observed/expected ratio (o/e) 0.74, 90% interval 0.64 to 0.85. Synonymous variants: 49 observed, 60.7 expected, observed/expected ratio (o/e) 0.81, 90% interval 0.64 to 1.02.
Homologues: Orthologues: guinea pig CAPZA1 (98% identical), mouse Capza1 (97% identical), macaque CAPZA1 (96% identical), rat Capza1 (94% identical), pig CAPZA1 (93% identical), tropical clawed frog capza1 (88% identical), zebrafish capza1a (81% identical), zebrafish capza1b (81% identical), mouse Capza1b (68% identical), rat 4933400A11Rik (68% identical), Drosophila melanogaster cpa (63% identical), Caenorhabditis elegans cap-1 (54% identical). Paralogues in human: CAPZA2 (87% identical), CAPZA3 (36% identical).
Diseases named in the same sentence as CAPZA1 in open-access papers:
CAPZA1 is named in the same sentence as 35 diseases in open-access papers, as found by Europe PMC text mining. Sharing a sentence is not in itself a finding about the gene and the disease. The quoted sentences say what the papers report.
gastric cancer (15 papers, 2013 to 2024). A primary or metastatic malignant neoplasm involving the stomach. "Low CAPZA1 expression levels have been associated with increased invasive phenotypes in gastric cancer and lung cancer." (PMID 38985526, 2024). "CAPZA1 is the α1 subunit of this complex and has been reported to regulate the autolysosome formation and its deregulation leads to higher risk of gastric cancer and metastasis." (PMID 38099196, 2023). "A recent study showed that CPα1 subunit (CAPZA1) down-regulation in gastric cancer was associated with poor prognosis and with increased cancer cell migration and invasion." (PMID 27391153, 2016). "In vitro, forced expression of CAPZA1 caused a significant decrease in gastric cancer cell migration and invasion, whereas CAPZA1 depletion had the opposite effect." (PMID 23545944, 2013). "The present study suggests that CAPZA1 could be a marker of good prognosis in gastric cancer and shows that CAPZA1 is associated with decreased cancer cell migration and invasion." (PMID 23545944, 2013). "Recent discoveries have suggested that CAPZA1 in various human tumors could regulate cell proliferation, metastasis, and epithelial–mesenchymal transition, and elevated CAPZA1 is closely linked to an unfavorable prognosis in gastric cancer." (PMID 36686785, 2022). "Further investigations of LRP1 and CAPZA1 polymorphisms and their functions are required to elucidate the pathophysiological differences between GMA and gastric cancer." (PMID 37198664, 2023). "CAPZB has oncogenic potential, CAPZA1 inhibits cancer cell migration in gastric carcinoma while CAPZA2 promotes gastric cancer cell migration and invasion." (PMID 36291816, 2022). "CAPZA1 encodes the α1 subunit of CAPZ and has been reported to play a role in gastric cancer metastasis." (PMID 28093067, 2017). "F-actin capping protein α1 subunit (CAPZA1) was previously identified in a proteomic analysis of human gastric cancer clinical specimens and selected for further study." (PMID 23545944, 2013). "In addition, hsa_circ_0001811 was low expressed in gastric cancer, and targeted the miR-589/CAPZA1 axis to inhibit the progression of gastric cancer." (PMID 39071490, 2024). "Because it was reported that CD2AP bound CAPZA1 to promote intercellular adhesion and to influence cell cytoskeleton in gastric cancer, there is a possibility that CD2AP also interacts with certain protein(s) in the NF-kB signaling to regulate the NF-kB activity." (PMID 39353894, 2024). "CAPZA1 is overregulated in hepatocellular carcinoma and gastric cancer." (PMID 39114022, 2024). "CAPZA1 is upregulated in hepatocellular carcinoma and gastric cancer." (PMID 35909892, 2022). "CAPZA1 promoted the expression of CD44 and epithelial splicing regulatory protein 1 (ESRP1), the latter which spliced CD44 into CD44 variant 9 (CD44v9), a marker of gastric cancer stem-like cells." (PMID 36526626, 2022). "Collectively, these results suggest that CAPZA1 may have prognostic value in gastric cancer." (PMID 23545944, 2013). "CAPZA1 expression in gastric cancer tissue may help determine treatment choice." (PMID 23545944, 2013).
hepatocellular carcinoma (9 papers, 2017 to 2025). A malignant tumor that arises from hepatocytes. "To further investigate the effect of Tks4 knockdown on CAPZA1 and its role in EMT induction, we employed a similar experimental setup as was used to study the role of CAPZA1 in hepatocellular carcinoma cells." (PMID 38985526, 2024). "Interestingly, CAPZA1 was also reported to inhibit EMT in hepatocellular carcinoma by regulating actin cytoskeleton." (PMID 40022181, 2025). "Moreover, in hepatocellular carcinoma cells, it was demonstrated that decreased expression of CAPZA1 drives the low oxygen-induced EMT process." (PMID 38985526, 2024). "Consistent with this, CAPZA1 overexpression inhibited the EMT process in hepatocellular carcinoma." (PMID 38985526, 2024). "The liver surface of mice in the sh-CAPZA1-expressing HepG2 group and MHCC97H control group were covered with micro-hepatoma lesions." (PMID 28093067, 2017). "Moreover, Huang and colleagues demonstrated that CAPZA1 inhibits epithelial mesenchymal transition (EMT) in hepatocellular carcinoma (HCC) cells by regulating actin filament assembly, thereby reducing the invasion and migration abilities of HCC cells." (PMID 38099196, 2023). "CAPZA1 is the α1 subunit of this complex, and we hypothesized that CAPZA1 regulates EMT through the regulation of actin filaments assembly, thus reducing the metastatic ability of hepatocellular carcinoma (HCC) cells." (PMID 28093067, 2017).
breast carcinoma (4 papers, 2013 to 2022). "SK2 KD universally downregulated expression of CAPZA1 (inhibition of autophagy and EMT) and also decreased expression of NSUN3, ADPGK and KLHDC10 in prostate and ITGAV in breast cancer cell lines." (PMID 30971929, 2019).
esophageal squamous cell carcinoma (3 papers, 2021 to 2026). Esophageal squamous cell carcinoma (ESCC) is a type of esophageal carcinoma (EC) that can affect any part of the esophagus, but is usually located in the upper or middle third. "CAPZA1 was downregulated by miR-875-5p in esophageal squamous cell carcinoma, causing a tumor-promoting function." (PMID 37888706, 2023).
pancreatic cancer (3 papers, 2016 to 2021). "It was also showed that F-actin formation was suppressed by UBR5 deficiency, suggesting that UBR5 enhanced pancreatic cancer migration and invasion via promoting CAPZA1 degradation-induced F-actin remodeling in pancreatic cancer cells." (PMID 33777788, 2021). "We further identified F-actin-capping protein subunit alpha-1 (CAPZA1) as a novel substrate of UBR5 and described a CAPZA1–related mechanism underlying the metastasis-promoting effect of UBR5 in pancreatic cancer." (PMID 33777788, 2021). "In our study, it was observed that the decrease in CAPZA1 was associated with marked increase in F-actin intensity in UBR5-overexpression pancreatic cancer cells that exhibited enhanced migratory and invasion ability." (PMID 33777788, 2021). "These in vivo data were consistent with our in vitro findings, supporting a metastasis-promoting effect of UBR5 via destabilizing CAPZA1 in pancreatic cancer." (PMID 33777788, 2021). "We therefore focused on CAPZA1 to explore the mechanism of UBR5-induced enhancement of pancreatic cancer cells migration and invasion." (PMID 33777788, 2021). "Using reciprocal Co-IP assays, the interaction of UBR5 with CAPZA1 was confirmed not only in HEK-293T cells but also in pancreatic cancer MIA PaCa-2 and BxPC-3 cells transfected with GFP-tagged UBR5." (PMID 33777788, 2021). "Therefore, targeting UBR5 or UBR5-mediated CAPZA1 ubiquitination will provide promising strategies for preventing cancer metastasis in pancreatic cancer patients, particularly in those with high UBR5 expression." (PMID 33777788, 2021). "We next investigated the influence of UBR5 on CAPZA1 expression in pancreatic cancer cells." (PMID 33777788, 2021). "Moreover, the confocal microscopy showed the co-localization of UBR5 and CAPZA1 in pancreatic cancer cells, further supporting the interaction between these two proteins." (PMID 33777788, 2021). "Given that CAPZA1 functions as the substrate of UBR5, we can reasonably speculate that CAPZA1 degradation-induced actin reorganization might contribute to UBR5-induced pancreatic cancer cells metastasis." (PMID 33777788, 2021). "This study, for the first time, described the cytoplasmic protein CAPZA1, an actin capping protein, as an important substrate of UBR5 and an important mediator of UBR5-induced cell migration and invasion in pancreatic cancer." (PMID 33777788, 2021). "In summary, the current study provides evidence demonstrating UBR5 as a potent metastasis promoter for pancreatic cancer and suggests that UBR5 exerts its metastasis-promoting effect via promoting the ubiquitination and degradation of CAPZA1." (PMID 33777788, 2021). "UBR5 knockdown significantly increased the intracellular level of CAPZA1 and CAPZA1 downregulation largely reversed the UBR5 knockdown-induced suppression of cell migration and invasion in pancreatic cancer cells." (PMID 33777788, 2021). "With respect to the mechanisms, our study identified CAPZA1 as a novel substrate of UBR5 and suggested that UBR5 mediated the ubiquitin-proteasome-dependent degradation of CAPZA1, which in turn facilitated pancreatic cancer metastasis via promoting F-actin remodeling." (PMID 33777788, 2021).
esophageal cancer (2 papers, 2021 to 2022). A primary or metastatic malignant neoplasm involving the esophagus. "Polymorphism rs11473 C > T at the 3′-UTR of BSG was significantly associated with a high risk of esophageal cancer, whereas polymorphism rs373245753 T > G at the CAPZA1 3′-UTR could disrupt the binding of miR-875-5p and the target CAPZA1." (PMID 36461008, 2022). "Additionally, we demonstrated that CAPZA1 CDS alone can directly inhibit the malignant phenotype of esophageal cancer, while miR-875-5p couldn’t reverse the suppressive effect of CDS on malignant phenotype of esophageal cancer." (PMID 33505778, 2021).
liver cancer (2 papers, 2015 to 2021). An epithelial or non-epithelial malignant neoplasm that arises from the liver. "It has been reported that, in gastric and liver cancer, the expression of CAPZA1 was significantly decreased, which contributed to an increased metastatic ability of cancer cells." (PMID 33777788, 2021).
lung carcinoma (2 papers, 2024). "We discovered that while Grb2 and cortactin are present to a lesser degree in the Tks4-formed complex, CD2AP and CAPZA1 are abundant in the tested three lung cancer cell lines." (PMID 38985526, 2024). "To understand the regulatory role of Tks4 in lung cancer, we performed a Tks4-interactome analysis via Tks4 immunoprecipitation-mass spectrometry on five different cell lines and identified CAPZA1 as a novel Tks4 partner protein." (PMID 38985526, 2024). "CAPZB overexpression has indeed been reported in epithelioid sarcoma tissue specimens, where it increased cell growth and motility, while CAPZA1 could regulate cell growth, invasion, and EMT markers in various human tumors, representing an unfavorable prognostic marker in gastric and lung cancers." (PMID 38607010, 2024).
asthenozoospermia (1 paper, 2026). "The CAPZA1 variant was further screened by Sanger sequencing in 20 infertile men with asthenozoospermia and 20 age-matched fertile controls." (PMID 41858859, 2026).
cardiac hypertrophy (1 paper, 2019). "Of these, MTPN drives the growth of cardiomyocytes and promotes cardiac hypertrophy, whilst reduced CAPZA1 improves post-ischemic cardiac function." (PMID 31086124, 2019).
colon cancer (1 paper, 2024). "The expression levels of CD2AP, GRB2, WASL, and CAPZA1 are generally downregulated, while those of SRC and CTTN are upregulated in colon cancer samples compared with their levels in normal samples at the RNA and/or protein levels." (PMID 39234565, 2024). "We entered the analyzed colon cancer marker gene set (CD2AP, GRB2, WASL, SRC, CTTN, CAPZA1, and Tks4) into this tool to elucidate which cancer hallmark-related pathways are influenced by these proteins." (PMID 39234565, 2024).
emphysema (1 paper, 2021). "The FEV1pp miRNA–mRNA networks and percent emphysema network share three genes (CAPZA1, CEP57, and SLC15A3) and eight miRNAs including hsa-miR-145-5p, hsa-miR-223-3p, hsa-miR-26b-3p, hsa-miR-338-5p, hsa-miR-1275, hsa-miR-150-3p, hsa-miR-150-5p, and hsa-miR-342-3p." (PMID 34777474, 2021).
gastritis (1 paper, 2025). Inflammation of the stomach. "When examining proteins correlated with the third component separating gastritis and preneoplasia, Capping Actin Protein of Muscle Z-Line Subunit a (CAPZA1), a-L-Fucosidase 2 (FUCA2), Endoplasmic Reticulum Aminopeptidase 2 (ERAP2), and LEP are found." (PMID 41155404, 2025).
glioma (1 paper, 2024). A benign or malignant brain and spinal cord tumor that arises from glial cells (astrocytes, oligodendrocytes, ependymal cells). "Differently, ANXA5 is regarded as a potential early biomarker in hepatocarcinogenesis together with ANXA2 and a predictive biomarker for tumor progression in different cancer types, but it was not so far identified as a specific oncogenic protein in gliomas as well as CAPZB and CAPZA1." (PMID 38607010, 2024).
lung adenocarcinoma (1 paper, 2022). A carcinoma that arises from the lung and is characterized by the presence of malignant glandular epithelial cells. "The Prognostic value of CAPZA1 in lung adenocarcinoma in PrognoScan." (PMID 36686785, 2022). "The correlation between lncRNA and CAPZA1 in lung adenocarcinoma." (PMID 36686785, 2022). "However, the immune-regulating role of CAPZA1 in the initiation and development of lung adenocarcinoma (LUAD) remains unclear." (PMID 36686785, 2022).
lymph node metastasis (1 paper, 2013). "CAPZA1 overexpression was associated with well differentiated histology, smaller tumor size, lower T stage, absence of lymph node metastasis, lower TNM stage, lower recurrence rate and longer survival time, compared to CAPZA1 underexpression." (PMID 23545944, 2013).
lymphoma (1 paper, 2022). A malignant (clonal) proliferation of B- lymphocytes or T- lymphocytes which involves the lymph nodes, bone marrow and/or extranodal sites. "The down-regulated CAPZA1, CAPZB, EFHD2, EZR and PCMT1 proteins are involved in cell–cell adhesion; their reduced levels are compatible with the metastatic behavior of lymphoma cells." (PMID 36291816, 2022).
metastatic tumors (1 paper, 2021). "In addition, we performed the immunohistochemistry analyses of UBR5 and CAPZA1 in metastatic tumors." (PMID 33777788, 2021).
oral squamous cell carcinomas (1 paper, 2013). "Differential expression of CAPZA1 has been reported in oral squamous cell carcinoma." (PMID 23545944, 2013). "A 10-fold increase in the expression of CAPZA1 was observed in HPV18-positive oral squamous cell carcinomas compared to other HPV18-positive cancers, although no overexpression was detected at the RNA level." (PMID 23545944, 2013).
prostate carcinoma (1 paper, 2020). A carcinoma that arises from epithelial cells of the prostate gland. "Based on mRNA expression levels, the CAPZA1/B2 heterodimer is more prominently expressed than the CAPZA2/B2 in the PC-3 prostate cancer cells, which were used in most of our cellular assays." (PMID 32771000, 2020). "To obtain information on CP localization in PC-3 prostate cancer cells, we analysed the subcellular distribution of endogenously expressed CAPZA1, CAPZA2 and CAPZB2 from fractionated cells by Western blotting." (PMID 32771000, 2020). "When we compared CP expression in different prostate cancer cell lines by Western blotting, we observed slightly lower levels of CAPZA1 in PC-3 cells as compared to the other lines, while CAPZB levels were highest in DU-145 cells." (PMID 32771000, 2020). "According to data from the Betastasis database, both CAPZA1 and CAPZB mRNA levels positively correlated with PIM1 in primary prostate cancer patient samples." (PMID 32771000, 2020). "We have identified capping proteins CAPZA1 and CAPZB2 as PIM1 substrates, and shown that phosphorylation of either of them leads to increased adhesion and migration of human prostate cancer cells." (PMID 32771000, 2020). "Here we show positive correlations between PIM1 and either CAPZA1, CAPZA2 or CAPZB mRNAs in prostate cancer samples with different Gleason grades, but not in the healthy control tissues." (PMID 32771000, 2020).